IL1B (interleukin 1 beta)
Diseases named in the same sentence as IL1B in open-access papers (continued):
Sharing a sentence is not in itself a finding about the gene and the disease.
glioma (continued). "IL-1β promotes the self-renewal and oncogenic ability of gliomas, while IL-6 and IL-8 activate oncogenic ability of breast and colon CSCs." (PMID 26824417, 2016). "IL1β from inflammatory monocytes has a paracrine effect on glioma cells and induces increased levels of CCL2 in tumor cells, which in turn has a paracrine effect on inflammatory monocytes, resulting in increased infiltration." (PMID 25987130, 2015). "IL1β promoted tumor growth and increased the cancer stem cell phenotype in murine and human Proneural glioma stem cells (GSCs)." (PMID 25987130, 2015). "This overexpression of IL1β in turn promotes glioma growth, induces activation of the p38 MAPK pathway, increases the GSC phenotype, and upregulates CCL2 expression, which correlates with greater monocyte infiltration." (PMID 25987130, 2015). "Accordingly, IL-1β represents a major inducer of this miRNA in both human astrocytes and glioma cells (; present data)." (PMID 25986346, 2015). "Together, these data suggest that monocytes and macrophages can drive elements of a stem cell phenotype in PDGFB-induced gliomas via IL1β expression." (PMID 25987130, 2015). "We provide evidence that human BMVEC (hBMVEC) IL-1β and IL-6 positively influence the expression of sCp transcript by neighboring C6 glioma cells (astrocytes)." (PMID 25311416, 2014). "Our data indicate that hBMVEC-secreted cytokines IL-1β and IL-6 activate sCp gene expression in C6 glioma cells." (PMID 25311416, 2014). "First, we confirmed by western blot that IL-1β and IL-6 incubated with C6 glioma cells for 6 h yielded an increase in the secretion of sCp from C6 glioma cells into the media." (PMID 25311416, 2014). "Of note is that the abundance of hBMVEC IL-6 and IL-1β transcripts were increased by co-culture in transwell with C6 glioma cells (respectively)." (PMID 25311416, 2014). "In contrast cytokines IFN-α, TNF-α,IL-12p70, IL-1β, IL-6, IL-8 and IL-10, as well as metalloproteinases -2 and -9 were present in equalamounts in glioma C6 and astrocyte CMs." (PMID 23637756, 2013). "Interleukin-1β (IL-1β) has been identified in reactive astrocytes in the glioma periphery, suggesting an anti-tumor immune response." (PMID 23596394, 2013). "Relocation of the nuclear protein to the cytoplasm has been shown to be induced in rat and human cultured astrocytes and glioma cells by IL-1β." (PMID 23270518, 2012). "In the present study, IL-1β treatment significantly decreased Kir4.1 mRNA levels in both the U373 glioma cell line and fetal astrocytes in culture." (PMID 23270518, 2012). "In both astrocytes-enriched human cell cultures and glioma cells incubated with IL-1β, immunocytochemistry demonstrated a lower percentage of Kir4.1-labeled cells as compared to controls." (PMID 23270518, 2012). "Our findings indicate that glioma cells that fail to self-renew to generate neurospheres in standard stem cell-enrichment conditions can gain this ability after exposure to IL-1β and TGF-β." (PMID 22330721, 2012). "IL-1β and TGF-β are elevated significantly in high grade gliomas and that has been associated with poor prognosis in glioma patients." (PMID 22330721, 2012). "IL-1β and TGF-β are highly expressed in malignant gliomas and associated with poor prognosis of glioma patients." (PMID 22330721, 2012). "In the present study, we find that midazolam significantly suppresses IL-1β-induced IL-6 release from C6 glioma cells." (PMID 21682888, 2011). "Taking our findings into account, it is most likely that midazolam inhibits IL-1β-induced IL-6 release through the JAK/STAT3 pathway suppression in C6 glioma cells." (PMID 21682888, 2011). "In conclusion, our findings strongly suggest that midazolam inhibits IL-1β-induced IL-6 release in rat C6 glioma cells via suppression of STAT3 activation." (PMID 21682888, 2011). "We previously reported that IL-1β significantly induces IL-6 mRNA expression and stimulates IL-6 release in C6 glioma cells." (PMID 21682888, 2011).
glioma (continued). "Second, application of SP or neurokinin A (NKA) to NK1R+glioma cell lines increased the secretion of interleukin 6 (IL-6) and potentiated IL-6 secretion induced by IL-1β." (PMID 9888463, 1999). "The M2 phenotype of macrophages secreted IL-1β, which led to the migration of glioma cells." (PMID 40727443, 2025). "Glioma cells produce various immunomodulatory factors, such as IL-1β, IL-6, TGF-β, and IL-8." (PMID 40927709, 2025). "Future studies employing single-cell RNA-seq or spatial transcriptomics could clarify the cellular origins of TNF-α, IL-1β in gliomas and their interaction with infiltrating immune cells." (PMID 40565357, 2025). "Additionally, the NLRP3 inflammasome can regulate the NF-κB p65 and IL-1β signaling to induce glioma cell invasion and proliferation." (PMID 41157253, 2025). "In glioma cells, IL1β increased the pro-inflammatory prostaglandin COX-2's mRNA expression." (PMID 40727443, 2025). "Our data highlight the TNF-α, IL-1β axis as a critical mediator of glioma progression." (PMID 40565357, 2025). "Furthermore, the insulin-like growth factor 1 (IGF-1) has been shown to trigger TLR9 expression in glioma cells through activation of hypoxia-induced factor 1 alpha signaling, which in turn stimulates IL-1β, IL-6, IL 8 as well as CXCR4." (PMID 41157253, 2025). "Furthermore, Glioma cells secrete immunomodulatory cytokines like IL-1β, IL-6, TGF-β, and IL-8 to activate or suppress immune response." (PMID 40927709, 2025). "To evaluate the combined impact of the developing glioma and SorLA loss from host cells on the tumor microenvironment, we first assayed the levels of selected cytokines (TNFα, MIP2, CCL5, CXCL1, IL1β, IL2, IL6, and IL10) in the tissue lysates derived from tumor-bearing and tumor-free hemispheres." (PMID 38499808, 2024). "Additionally, high expression of CD133 in gliomas facilitates the recruitment of neutrophils by modulating the regulation of IL-1β and its downstream chemotactic factors." (PMID 38779679, 2024). "This implied that CASP4 may be involved in immune cell migration in gliomas by regulating IL-1β protein expression." (PMID 39075190, 2024). "Mesenchymal (MES) cellular state could be induced in glioma stem cells (GSCs) by IL-1β, which may also greatly improve the self-renewal capacity of GSCs." (PMID 38779679, 2024). "The antitumor effect of this molecule can also be observed in an indirect coculture model (via glioma conditioning medium), inducing microglial regulation to a pro-inflammatory profile by increasing the expression levels of cytokines such as IL-1β, IL-6, and IL-18." (PMID 38248305, 2024). "Additionally, P2X7R upregulation in glioma-associated microglia drives immunosuppression upon facilitating NLRP3 inflammasome activation and IL-1β release." (PMID 38247852, 2024). "IL-1β plays a relevant role in the activation of various signaling pathways, including the NFκB transcription factor, which regulates the production and release of pro-inflammatory mediators essential for the development and progression of glioma." (PMID 38248305, 2024). "The constitutive expression of both IL-1β and IL-1Ra has been reported in human glioma cells." (PMID 38003396, 2023). "IL-1β coordinates the progression of neuroinflammation by upregulating the expression of other pro-inflammatory cytokines, whereas TNFα induces the expression of vascular endothelial growth factor in gliomas, leading to increased angiogenesis seen in GBM." (PMID 38003396, 2023). "Interestingly, in glioma or melanoma, TMZ-induced upregulation of NLRP1 and IL-1β is linked to the Notch1 signaling pathway and, subsequently, to the acquisition of drug resistance, as revealed by MAPK inhibitors." (PMID 37723542, 2023).
glioma (continued). "Glioma-derived factors, such as IL-1β, IL-6, IL-8, and TNFα, are crucial inflammatory mediators that trigger the inflammatory cycle in GBM and also promote carcinogenesis by avoiding growth suppression and apoptosis, inducing angiogenesis and metastasis and maintaining cancer cell stemness." (PMID 38003396, 2023). "Furthermore, glioma-derived cytokines IL-1β, IL-6, and TNFα were observed to extend neutrophils lifespan from 7 h in normal conditions to 17 h in cancer, which in turn increases the number of neutrophils in peripheral blood." (PMID 38003396, 2023). "Then, IL-1β expression in glioma cells promotes TANs recruitment." (PMID 35860278, 2022). "In addition, a very recent study showed that monocyte-derived macrophages in gliomas secrete IL1β in response to tumor cell induction, while Il1b knockdown significantly prolonged the survival time of primary glioma mice." (PMID 36199426, 2022). "Recent research showed that the knockdown of NLRP3 could inhibit the growth and invasion of glioma cells, along with the decrease of IL-1β and NF-κB, indicating a positive correlation between NLRP3 and NF-κB." (PMID 36401196, 2022). "Furthermore, ICAM-1 and VCAM-1 play important roles in the adhesion of cancer cells to the endothelium, especially in the context of the inflammatory microenvironment, supported by the high concentration of IL-1b, correlated with higher grade gliomas." (PMID 35741603, 2022). "Interleukin 1-β (IL-1β), secreted from the M2 macrophages, phosphorylates the key glycolytic enzyme glycerol-3-phosphate dehydrogenase of glioma cells which increases the substrate affinity and glycolytic metabolism of the glioma cells and promotes tumorigenesis." (PMID 35884391, 2022). "Furthermore, IL-1β contributes to the development of a microenvironment that is favorable to glioma migration and invasion." (PMID 35057010, 2022). "After exposure to IL-1β, C6 glioma cells were treated with various doses of EPA." (PMID 34944727, 2021). "In addition, glioma cells display aberrant expression of IL-1β, and NLRP3 seems to contribute to radiotherapy resistance." (PMID 34064909, 2021). "IL-1β upregulated mRNA expression of pro-inflammatory prostaglandin COX-2 in glioma cells." (PMID 34439380, 2021). "Interleukin 1β (IL-1β) released by TAMs reprograms cellular metabolism by boosting glycolysis of glioma through the IL-1β-protein kinase-delta (PKCδ)-glycolytic enzyme glycerol-3-phosphate dehydrogenase (GPD2) axis, which promotes tumor proliferation and tumorigenesis." (PMID 34671362, 2021). "Interestingly, exosomes from U87 cells that were stimulated by the cytokine IL-1β, produced enhanced effects, indicating a dose-dependent response by the glioma exosomes." (PMID 32649728, 2020). "However, in the presence of primers such as IL-1β and IFN-γ, cytokines that are commonly elevated in glioma patients, demeclocycline had stimulatory properties beyond that of when either IL1β or IFN-γ were administered alone." (PMID 32153581, 2020). "In this study, we confirmed that LINC01116 could promote glioma proliferation and neutrophil recruitment by regulating IL-1β, providing new insights into the lncRNAs-mediated progression of glioma." (PMID 32358484, 2020). "Interestingly, the gene expression of markers connected to a pro-inflammatory response, Il1b and Nos2, were also detected at high levels in glioma-infiltrating cells." (PMID 32555306, 2020). "Furthermore, LINC01116 induced IL-1β expression in glioma cells to promote tumor proliferation and recruit TANs, which participated in the pro-tumor process via producing a host of cytokines." (PMID 32358484, 2020). "Moreover, we observed upregulation of IRF7 mRNA and Il1b mRNA in human microglia upon stimulation with CSF2-depleted LN18 or U87 glioma cells, respectively, relative to treatment with shNeg-conditioned medium." (PMID 32390004, 2020).
glioma (continued). "Our findings reveal that LINC01116 can promote glioma proliferation and neutrophil recruitment by regulating IL-1β, and may be served as a novel target for glioma therapy and prognosis." (PMID 32358484, 2020). "TNF-α and IL-1β can serve as key prognostic biomarker in high-grade glioma and meningioma patients." (PMID 31653130, 2019). "We speculated that downstream of IL-1β, NF-κB signaling is likely to be responsible for glioma metastasis and tumor EMT as target genes of NF-κB, such as MMPs and vascular endothelial growth factors, are highly associated with tumor invasion." (PMID 31139563, 2019). "Since our clinical study confirmed that glioma samples have an upregulated protein expression of IL-1β and IL-18, we questioned whether inhibition of the production of IL-1β and IL-18 leads to glioma cell death." (PMID 31139563, 2019). "Moreover, IL-1β production has been shown to increase the expression of other cytokines in glioma microenvironment, such as IL-6 and IL-8, which also have crucial role in tumor development." (PMID 31231208, 2019). "Furthermore, it has been suggested that IL-1b induces changes affecting the glioma microenvironment in favor of increased tumor invasion, migration and angiogenesis." (PMID 30647842, 2018). "Finally, reduced endogenous miR-181d and increased IL-1b/CCR1 levels were identified in IGF-1-stimulated glioma cells." (PMID 28389653, 2017). "In addition to hypoxia, HIF-1α can also be activated in response to protoinflammatory mediators such IL-1β and plays a key role in glioma progression." (PMID 28781970, 2017). "It was also of interest to determine whether the effect of IL1β on the glioma stem cell phenotype occurs in human GSCs." (PMID 25987130, 2015). "We therefore examined whether IL1β-treated glioma cells that were maintained in GSC-enriching medium would show an increase in the glioma stem cell population in vitro." (PMID 25987130, 2015). "In our study, we showed induction of miR155 in response to IL-1β in glioma cells." (PMID 25986346, 2015). "Since our data showed that IL1β regulates CCL2 mRNA expression in glioma cells, we examined whether there was a correlation between IL1β and CCL2 mRNA expression levels in human GBM subtypes (from TCGA database) and murine GBM." (PMID 25987130, 2015). "We previously reported that IL-1β induces activation of STAT3 in C6 glioma cells." (PMID 21682888, 2011). "We have previously reported that IL-1β significantly induces IL-6 synthesis in C6 glioma cells." (PMID 21682888, 2011). "However, the expression of il-1β was up-regulated in CD11b+ cells from gliomas, this increase was smaller in comparison to 25-fold increase in the il-1β mRNA level in CD11b+ cells from LPS-injected brains (not shown)." (PMID 21901144, 2011). "Leptin has been shown to induce or to potentiate together with interferon γ (IFNγ), with tumor necrosis factor α (TNFα) or with IFNγ and IL-1β, NO production in murine J774A.1 macrophages, rat adipocytes, C6 glioma cell-line, and rat vascular smooth muscle cells (VSMCs)." (PMID 19688109, 2009). "In addition, a Kaplan–Meier (KM) survival analysis was conducted on the core genes in liver cancer, renal clear cell carcinoma, and glioma, and it was found that TNF, IL6, IFNG, and NR1H4 in liver cancer and TNF and IL1B in renal clear cell carcinoma were associated with survival prognosis." (PMID 40238193, 2025). "Moreover, under the influence of glioma cells, GAMs become a major source of molecules (e.g., interleukin-1 beta (IL-1β), interleukin-10 (IL-10), vascular endothelial growth factor (VEGF)) that support tumor growth and contribute to an immunosuppressive tumor microenvironment." (PMID 37368789, 2023). "Furthermore, we observed that GAMs in IDHmt gliomas exhibited a significant increase in the expression of M1‐associated markers and cytokines, such as CD86 and IL1B, and a significant decrease in M2‐associated genes, such as CD163 and CD206, relative to IDHwt counterparts." (PMID 37166058, 2023).
glioma (continued). "Macrophages are recruited to the glioma environment to create a supportive stroma for glioma cell proliferation, survival, and migration through immune functions, such as the release of transforming growth factor-β, epidermal growth factor, interleukin (IL)-6, and IL-1β." (PMID 34660294, 2021). "LINC01116, IL-1β, and TANs may be served as biomarkers and targets for glioma immunotherapy." (PMID 32358484, 2020). "In addition, IL-1β could significantly promote the self-renewal of glioma stem cells, and trigger the transition of glioma-initiating cells into a mesenchymal (MES) cell state." (PMID 32358484, 2020). "However, in the presence of the exosomes from untreated or IL-1β-treated U87 cells, significantly more cells differentiated into astrocytes, especially in the presence of exosomes obtained from the IL-1β-challenged glioma cells." (PMID 32649728, 2020). "Next we examined whether CCL2 is upregulated by IL1β treatment in cultured glioma cells." (PMID 25987130, 2015). "Thus, production of IL-1β by tumor astrocyes may (through different mechanisms) contribute to the epileptogenicity of glial tumors." (PMID 23270518, 2012). "In glioma, LPS not only upregulates inflammatory mediators such as IL-8, CXCL8, and IL-1β to support tumorigenesis but also alters the immunophenotype of glioma cells and induces antitumor immunity via TLR4." (PMID 40444051, 2025). "The proangiogenic compounds involved in the development of glioma include hypoxia-inducible factor 1α (HIF-1α), angiopoietin-2 (ANG-2), and interleukin-1β (IL-1β)." (PMID 40429943, 2025). "Tests for glioma based on the determining concentrations of HIF-1α, ANG-2, and IL-1β will indicate the presence of the disease at higher concentrations of these proteins, because the diagnostic value of each variable increases with concentration." (PMID 40429943, 2025). "IL-1, including IL-1β, potently induces tumour angiogenesis and invasion by promoting the release of VEGF and MMPs by glioma cells as well as the polarisation and recruitment of immunosuppressive TAMs." (PMID 41034696, 2025). "WB results exhibited relative protein expression levels of NOD1, RIP2, Iba1, IL‐1β, and CD206 in glioma tissues in the Glioma group that were higher than in the Sham group (p < 0.05), with decreased expression following ML130 treatment." (PMID 41363048, 2025). "Compared with the Glioma group, the expressions of NOD1, RIP2, Iba1, IL‐1β, and CD206 in the Glioma + ML130 group were all decreased." (PMID 41363048, 2025). "All three collectively contribute to a pro-tumorigenic glioma TME, despite IL-10 being anti-inflammatory and IL-1β and IL-6 being pro-inflammatory." (PMID 41157253, 2025). "As expected, the conditioned medium from either GL261 or ALTS1C1 glioma cells significantly activated BV2 cells with a notable increase in pro-inflammatory cytokines, including IL-6, CCL-2, CXCL-10, MMP-14, TNFα, IL-1β, and iNOS." (PMID 41367876, 2025). "The WB result indicated that the relative expression of RIP2, Iba1, IL‐1β, and CD206 increased in glioma tissues, with higher expression in high‐grade gliomas than in low‐grade gliomas (p < 0.05)." (PMID 41363048, 2025). "The results indicated that NOD1, RIP2, Iba1, IL‐1β, and CD206 were highly expressed in glioma tissues, with higher expression in high‐grade gliomas than in low‐grade gliomas." (PMID 41363048, 2025). "The IHC results showed that in the Glioma + ML130 group, the OD values of NOD1, RIP2, Iba1, IL‐1β, and CD206 were lower than those in the Glioma group (p < 0.05)." (PMID 41363048, 2025). "The release of cytokines, including IL-12, IL-1B, CCL8, and IL-6 by TAMs, has also been shown to promote glioma stem cell renewal." (PMID 38254796, 2024). "Other mediators, such as IL-1β and the long noncoding RNA LINC01116, also contribute to neutrophil recruitment by glioma cells." (PMID 38732975, 2024).